ADH6 (alcohol dehydrogenase 6 (class V))
Description:
Alcohol dehydrogenase. Catalyzes the NAD-dependent oxidation of primary alcohols to the corresponding aldehydes. Oxidizes secondary alcohols to the corresponding ketones (By similarity).
Synonyms: ADH-5
Tractability: Small molecule: an approved drug acts on it; it belongs to a druggable protein family.
Gene: Protein-coding gene on chromosome 4 (99,202,436 to 99,219,537, reverse strand). Ensembl gene ENSG00000172955.
Subcellular location: Cytoplasm
Pathways (Reactome):
Metabolism: Ethanol oxidation
Gene Ontology:
Molecular function: alcohol dehydrogenase (NAD+) activity; all-trans-retinol dehydrogenase (NAD+) activity; zinc ion binding; oxidoreductase activity
Biological process: retinoic acid metabolic process; retinol metabolic process
Cellular component: extracellular exosome; cytosol; cytoplasm
Genetic constraint (gnomAD): Loss-of-function variants: 32 observed, 34.04 expected, observed/expected ratio (o/e) 0.94, 90% interval 0.71 to 1.26. The upper end of that interval is the gene's LOEUF score, 1.26, which puts it in group 5 of 6, group 1 being the genes least tolerant of losing a copy. Missense variants: 425 observed, 444.44 expected, observed/expected ratio (o/e) 0.96, 90% interval 0.88 to 1.04. Synonymous variants: 157 observed, 156.2 expected, observed/expected ratio (o/e) 1.01, 90% interval 0.88 to 1.15.
Homologues: Orthologues: chimpanzee ADH6 (99% identical), macaque ADH6 (95% identical), rabbit ADH6 (79% identical), rat Adh6 (65% identical), tropical clawed frog adh6 (60% identical), mouse Adh6b (59% identical), rat Adh1-ps1 (57% identical), tropical clawed frog adh1c (57% identical), tropical clawed frog adh1 (56% identical), tropical clawed frog adh1a (56% identical), zebrafish zgc:77938 (53% identical), zebrafish adh8a (53% identical), and 7 more. Paralogues in human: ADH1B (63% identical), ADH1A (63% identical), ADH1C (63% identical), ADH7 (60% identical), ADH5 (59% identical), ADH4 (58% identical), CRYZ (24% identical), TP53I3 (20% identical), RTN4IP1 (19% identical), SORD (19% identical), MECR (17% identical), VAT1 (17% identical), and 5 more.
Diseases named in the same sentence as ADH6 in open-access papers:
ADH6 is named in the same sentence as 15 diseases in open-access papers, as found by Europe PMC text mining. Sharing a sentence is not in itself a finding about the gene and the disease. The quoted sentences say what the papers report.
pancreatic cancer (5 papers, 2021 to 2023). "It has been substantiated that ADH6 is involved in the P450-related pathway and biological processes linked to the progression and treatment of pancreatic cancer." (PMID 36930359, 2023). "The possible underlying mechanisms of ADH6 in pancreatic cancer have been discovered in previous studies." (PMID 33688464, 2021). "ADH6 is downregulated in hepatocellular carcinoma and is an important prognostic marker of pancreatic cancer." (PMID 36177002, 2022). "Hepatocellular carcinoma exhibits downregulation of the ATP synthesis-related gene alcohol dehydrogenase 6 (ADH6), which is a key prognostic indicator for pancreatic cancer." (PMID 36814901, 2023).
breast carcinoma (3 papers, 2021 to 2025). "For luminal A breast cancer, we observed that genes associated with favourable prognosis—including key regulators of glucose metabolism HK3, LDHAL6A, apoptosis regulator PRKCB, and alcohol dehydrogenase ADH6—are not directly targeted by current treatments." (PMID 41007296, 2025).
hepatocellular carcinoma (3 papers, 2021 to 2023). A malignant tumor that arises from hepatocytes. "In human hepatoma cells, expression of ADH6 is reportedly suppressed by miR-1301-3p, while expression of ADH4 was increased by miR-148a-3p." (PMID 34441974, 2021). "On the other hand, there are only two reports on regulation of alcohol dehydrogenase (ADH) by miRNA: in human hepatoma cells, miR-1301-3p suppressed expression of ADH6, while miR-148a-3p promoted ADH4 expression." (PMID 34441974, 2021).
alcohol dependence (2 papers, 2020 to 2022). Physical and psychological dependence on alcohol. "The 13th SNP and the 20th SNP are within in the region of gene ADH6, which is also known as an alcohol dependence gene." (PMID 32093702, 2020).
Alzheimer disease (1 paper, 2021). A progressive, neurodegenerative disease characterized by loss of function and death of nerve cells in several areas of the brain leading to loss of cognitive function such as memory and language.
bone cancer (1 paper, 2021). A primary or metastatic malignant neoplasm affecting the bone or articular cartilage.
ovarian carcinoma (1 paper, 2021). A malignant neoplasm originating from the surface ovarian epithelium.
pancreatic adenocarcinoma (1 paper, 2020). "Primarily, our results revealed that the expression levels of ADH1A-ADH4, and ADH6 were significantly decreased in HCC tissues compared to normal liver tissues, which were similar to their expression in non-small cell lung cancer (NSCLC) and pancreatic adenocarcinoma." (PMID 33287761, 2020).
tumor (13 papers, 2012 to 2025). "Subsequently, we used RT-qPCR to detect the mRNA expression of the ADH6 gene in three KIRC tumor samples and three normal kidney samples and plotted relative histograms." (PMID 33688464, 2021). "The extended in vivo circulation time of ADH-6 facilitates increased accumulation in tumor tissue and enhanced anticancer activity." (PMID 34172723, 2021). "The results showed that the expression level of the ADH6 gene in KIRC tumor tissue was significantly lower than that in normal kidney tissue." (PMID 33688464, 2021). "The effects of the oligopyridylamides were recapitulated in mice bearing SK-BR-3 xenografts, with ADH-6 again reducing tumor growth substantially compared to ADH-1." (PMID 34172723, 2021). "The relatively long in vivo circulation time of ADH-6 should facilitate greater accumulation in tumor tissue." (PMID 34172723, 2021). "Conversely, both ADH-6 and ReACp53 reduced tumor growth relative to the saline-treated control group." (PMID 34172723, 2021). "Histological analysis of tumor tissues using hematoxylin and eosin (H&E) staining confirmed the higher potency of ADH-6 compared to ReACp53 against MIA PaCa-2 xenografts." (PMID 34172723, 2021). "Our results showed that the expression level of ADHs including ADH1A, ADH1B, ADH1C, and ADH6 was obviously decreased with the progression of tumor malignancy." (PMID 33287761, 2020). "However, ADH-6 was markedly more effective at decreasing MIA PaCa-2 tumor volume and mass, and prolonging survival, compared to ReACp53." (PMID 34172723, 2021). "These ER+ tumours also demonstrate metabolic optimization through regulators such as HK3, LDHAL6A, ADH6, and PRKCB, which collectively shift metabolism toward greater efficiency." (PMID 41007296, 2025). "Therefore, we speculate that ADH1A-ADH4, and ADH6 may serve as tumor suppressors in HCC." (PMID 33287761, 2020). "In addition, tumor cells need to increase their efficiency by increasing glucose transporters, or various key enzymes, such as hexokinase 2 (HK2), pyruvate kinase M2 (PKM2), lactate dehydrogenase A (LDHA), aldolase C (ALDOC), alcohol dehydrogenase gene (ADH6)." (PMID 39438468, 2024). "While treatment with ADH-6 or ReACp53 did not have a significant effect on growth of the MCF-7 xenografts, both the protein mimetic and peptide markedly reduced the MIA PaCa-2 tumor growth relative to the vehicle-treated control group." (PMID 34172723, 2021).
cancer (6 papers, 2013 to 2023). A tumor composed of atypical neoplastic, often pleomorphic cells that invade other tissues. "The serum levels of alcohol dehydrogenase 6 (ADH6) have been shown in numerous studies to be a potential diagnostic marker in cancers." (PMID 36930359, 2023). "On the other hand, the hypermethylation of ADHFE1 further reduced the expression of neighbouring proteins, ADH6, ADH7, as well as ADH1A, in which the genes were associated with the patient’s prognosis and cancer pathogenesis." (PMID 35054365, 2022). "Additionally, phosphoproteome analysis showed that ADH-6 downregulates key cancer-promoting phosphoproteins that are known to be directly negatively regulated by p5358–62." (PMID 34172723, 2021). "Moreover, various cancer studies (secretome analysis) have reported differential expression of ADH6 in HCC-specific cell lines, sera and liver tissues indicating its specificity and sensitivity in detecting HCC." (PMID 26414287, 2015).
ADH6 also shares sentences with these, for which no sentence is quoted: alcoholic liver diseases (1 paper); alcoholism (1); cholestasis (1); liver cancer (1); type II diabetes (1).